APP (amyloid beta precursor protein)
Diseases named in the same sentence as APP in open-access papers (continued):
Sharing a sentence is not in itself a finding about the gene and the disease.
endothelial dysfunction (13 papers, 2012 to 2025). In vascular diseases, endothelial dysfunction is a systemic pathological state of the endothelium (the inner lining of blood vessels) and can be broadly defined as an imbalance between vasodilating and vasoconstricting substances produced by (or acting on) the endothelium. "In order to make the model more clinically relevant with an element of endothelial dysfunction, we generated APP/PS1/eNOS+/− mice by crossing complete eNOS deficient (eNOS−/−) mice and APP/PS1 mice." (PMID 35806318, 2022). "Loss of APP expression results in altered cellular response to environmental stimuli and leads to endothelial dysfunction." (PMID 33228083, 2020). "Therefore, increased APP processing and Aβ production may be directly linked to endothelial dysfunction in cerebral and peripheral blood vessels." (PMID 32407295, 2020). "This has led us to develop a new model by adding partial eNOS deficiency to APP/PS1 mice, a more clinically relevant model for early-stage AD with endothelial dysfunction." (PMID 35806318, 2022). "APP/PS1/eNOS+/− mice offer a more clinically relevant model for early-stage AD with an element of endothelial dysfunction to better understand the disease pathogenesis and to develop preventive and/or therapeutic strategies." (PMID 35806318, 2022). "Our results suggest that impairment of α-processing and shift to amyloidogenic pathway of APP contribute to endothelial dysfunction induced by senescence." (PMID 29348391, 2018). "Over-expression of APP in Tg2576 mice has been demonstrated to lead to endothelial dysfunction, thereby mitigating endothelial vasorelaxation with a concomitant decrease in bioavailable NO2." (PMID 29374229, 2018). "The present study, for the first time, demonstrated that partial eNOS deficiency exacerbated behavioral dysfunction, Aβ brain deposition, and microglial pathology in APP/PS1 mice, further implicating endothelial dysfunction in the pathogenesis of AD." (PMID 35806318, 2022). "However, the role of APP processing and Aβ production in endothelial dysfunction in obesity and diabetes is not clear." (PMID 32407295, 2020).
Glucose intolerance (13 papers, 2015 to 2024). Glucose intolerance (GI) can be defined as dysglycemia that comprises both prediabetes and diabetes. "We also evaluated predicted signaling from myofibroblast and preadipocytes to IMs, which showed increased MHC-II, CD99, MIF, periostin, amyloid beta precursor protein (APP), and CSF signaling pathways with glucose intolerance and have been implicated in macrophage polarization." (PMID 37711619, 2023). "Long-term HFD consumption in APP/PS1 males also induced glucose intolerance, increased levels of plasma insulin and decreased levels of glucose transporters (GLUT) 2 in the liver and GLUT 4 in skeletal muscle." (PMID 37686722, 2023). "Here, we demonstrated that central acute blockade of IL-6 rescued glucose intolerance, plasma IL-6 concentration and memory performance in APP/PS1 mice, indicating a central role of IL-6 in memory and metabolic dysregulations in AD71,72." (PMID 33911072, 2021). "Even though APBB2 (amyloid beta A4 precursor protein-binding, family B, member 2) primarily binds to APP, knocking out APBB2 in mice causes glucose intolerance and β-cell dysfunction." (PMID 34002691, 2021). "First, when fed an HFD, the weight gain and glucose intolerance in APP/PS1(A246E) double-transgenic mice became more severe than in wild-type mice and PS1(A246E) single-transgenic mice." (PMID 26244977, 2015). "Glucose intolerance was further verified in two transgenic mouse models of AD, namely 3xTg-AD and APP/PS1 mice." (PMID 25617315, 2015). "i.c.v treatment with infliximab, a TNF-α neutralizing antibody, further prevented glucose intolerance in AβO-injected mice and in APP/PS1 mice." (PMID 25617315, 2015). "However, glucose intolerance in OGTT was increased in 6-month-old APP/PS1 mice on STD compared to WT on STD, and was even more pronounced in APP/PS1 fed HFD, similarly to the study of Lee." (PMID 37686722, 2023). "Finally, inhibition of brain STAT3 signaling by i.c.v. treatment with AG490 normalized peripheral glucose tolerance in AβO-infused mice, and i.c.v. treatment with anti-IL-6 reversed glucose intolerance in APP/PS1 mice." (PMID 33911072, 2021). "APP × NSY fusion mice displayed marked glucose intolerance compared to their control groups." (PMID 32503113, 2020). "Importantly, APP/PS1-ob/ob mice showed severe glucose intolerance in the glucose tolerance test (GTT) when compared to the glucose intolerance of APP/PS1 mice at 12 weeks of age (p < 0.05)." (PMID 28467789, 2017). "Finally, we tested whether infliximab treatment would alleviate glucose intolerance in APP/PS1 mice." (PMID 25617315, 2015). "APP/PS1-fed HFD mice had more pronounced IR, glucose intolerance and liver steatosis than their WT controls." (PMID 37686722, 2023). "When we placed mice on a 60 % HFD, we found that male APP/PSEN1, display evidence of transient elevated fasted plasma insulin as well as both glucose intolerance and insulin insensitivity." (PMID 26916443, 2016). "This is consistent with previous studies where APP/PSEN1 mice have increased fasted insulin, develop glucose intolerance and become less insulin sensitive when placed on a HFD." (PMID 26916443, 2016). "Interestingly, age matters, as 4 weeks of HFD increased plasma glucose and insulin levels in 12-month-old male Tg APP/PS1 mice, while mice of 6 months of age had similar blood glucose levels compared to WT mice, in parallel with glucose intolerance." (PMID 35958733, 2022). "When they crossed AD-related human APP transgenic mice to human IAPP homozygote animals, this study found that the novel double transgenic mouse model was markedly hyperglycemic, exhibiting severe insulin resistance and glucose intolerance, accompanied by exacerbated brain pathology." (PMID 32503113, 2020). "Hence, the condition of constitutive glucose intolerance could determine a desensitized response to amyloid, which was maintained instead in APP-null mice lacking endogenous amyloid." (PMID 26300732, 2015).
Gliosis (12 papers, 2014 to 2025). Gliosis is the focal proliferation of glial cells in the central nervous system. "Collectively, these results indicate that CLU overexpression is associated with reduction of both neuritic dystrophy and gliosis, which is accompanied by decrease in Aβ accumulation in APP/PS1AAV-CLU mice compared with APP/PS1AAV-GFP mice." (PMID 33246484, 2020). "In the present experiments, from 81–160 dpi we found gliosis, white matter vacuolation and detection of APP associated with PrPres plaques in tg44 mice." (PMID 24447368, 2014). "Using this innovative model, we demonstrate for the first time that deletion of APP exacerbates tau aggregation, amyloid deposition, and gliosis compared to control 5xFAD×Tg30 mice." (PMID 40001463, 2025). "Gliosis, Drusen and APP/Aβ deposition represent common markers of neurodegeneration in AMD and AD retinas, resulting from damaged RGCs, activated Macroglia (Muller Cells and astrocytes) and reactive Microglia." (PMID 36466614, 2022). "Here, we depleted platelets in one-year-old APP Swedish PS1 dE9 (APP-PS1) transgenic mice for five days, using intraperitoneal injections of an anti-CD42b antibody, and assessed changes in cerebral amyloidosis, plaque-associated neuritic dystrophy and gliosis." (PMID 36734880, 2023).
cerebrovascular disease (11 papers, 2010 to 2024). "The present report highlights the pathological and clinical features of a concomitant cerebrovascular disease and amyloid precursor protein (APP) accumulation in the brain of a dog." (PMID 30482198, 2018). "It has been suggested that cerebrovascular disease, vascular dementia and AD share common pathophysiological cascades such as altered APP processing, perturbed energy metabolism and pathological immune response." (PMID 28210211, 2017). "To determine the effect of cerebrovascular disease on amyloid pathology, we induced HHcy in APP/PS1 transgenic mice." (PMID 24991237, 2014). "Histological examination of the brain along with immunohistochemistry results showed a concomitant APP, which is an Aβ precursor, accumulation within the neuroparenchyma and vessels (CAA) with histological evidences of a cerebrovascular disease in an aged dog." (PMID 30482198, 2018).
Hyperinsulinemia (11 papers, 2017 to 2025). An increased concentration of insulin in the blood. "IR leads to neural and cognitive abnormalities in the brain, predisposing it to cognitive dysfunction through hyperinsulinemia, impaired insulin signaling, and altered Amyloid Precursor Protein (APP) metabolism." (PMID 39859201, 2025). "These, observations suggest that prevention of hyperinsulinemia and improved adipose tissue lipid metabolism protects the liver from fat synthesis and accumulation in APP/PS1 mice expressing E4orf1." (PMID 37573386, 2023). "Overall, western diet-fed APP/PS1 mice were characterized by hyperinsulinemia, and neuroinflammation like our previously reported genetic model of comorbid AD." (PMID 34393764, 2021). "In addition, PKCι/λ downstream of insulin signaling is hyperactive and increases BACE1-cleavage of APP and Aβ production in hyperinsulinemia." (PMID 40551140, 2025).
ischemic stroke (11 papers, 2012 to 2025). A stroke disorder caused by obstruction of blood flow to the brain, due to thrombotic (local blood clot formation) or embolic (due to a blood clot or other material traveling from another site) event. "Paeonol was also found to protect against memory loss after ischemic stroke by reducing amyloid precursor protein (APP), beta-site APP cleaving enzyme (BACE), and apoptosis." (PMID 26821004, 2016). "In this study, we tracked the body weight changes of mice across eight experimental groups, including both male and female WT and APP/PS1 mice after ischemic stroke induction." (PMID 40141679, 2025). "In ischemic stroke survivors with disabilities and deficits, changes in the levels of amyloid precursor protein (APP) and tau protein, and expression of β-secretase, presenilin 1, and presenilin 2 are evident." (PMID 40629391, 2025). "Specifically, CR4+ microglia emerging one week post injury in the thalamus of mice exposed to ischemic stroke showed increased expression of several phagocytic markers similar to that described in aged APP/PS1 mice." (PMID 37308987, 2023). "APP and Aβ peptides are involved in cerebral hemostasis, capillary blood flow, thrombotic and fibrinolytic events, and hemorrhagic and ischemic strokes." (PMID 36979388, 2023). "The data revealed that paeonol protected memory after ischemic stroke via reducing APP, BACE, and apoptosis." (PMID 22474531, 2012). "In conclusion, we speculate that paeonol protected memory after ischemic stroke via reducing APP, BACE, and apoptosis." (PMID 22474531, 2012).
Sepsis (11 papers, 2011 to 2025). Sepsis is defined as life-threatening organ dysfunction caused by a dysregulated host response to infection. "EarlySepsis and WT-Sepsis animals explored shorter distances of 1512.13 ± 534.03 cm (p = 0.0049) and 1241.17 ± 228.81 cm (p = 0.0016), respectively, compared with APP-Sham animals (3048.52 ± 706.48 cm)." (PMID 36135174, 2022). "As such, APP-mice were subjected to a polymicrobial abdominal infection resulting in sepsis at 2 (EarlySepsis) and 4 (LateSepsis) months of age." (PMID 36135174, 2022). "Cortical astrogliosis was observed in the LateSepsis animals (4.84 ± 3.10 %) compared with WT-Sepsis animals (6.80 ± 2.16%, p = 0.0028), EarlySepsis animals (1.94 ± 1.11%, p = 0.0032), APP-Sham animals (2.77 ± 0.47%, p = 0.048)." (PMID 36135174, 2022). "As enabling an ATP-induced IL-1β release can prevent infection and fatal sepsis, we believe that we discovered one of the vital functions of APP and its peptides that contributed to their striking conservation during evolution." (PMID 32906646, 2020). "Similarly, lipid-regulating enzymes ANXA1, S100A8, and FABP5 are co-regulated in a network with ApoE and APP in response to sepsis." (PMID 38653992, 2024). "However, investigations into the function of the APP → CD74 axis in sepsis remain limited." (PMID 40625751, 2025). "Compared to the control group, signaling pathways such as ANNEXIN, CCL, and CADM showed enhanced relative information flow in sepsis samples, whereas classical immune-related pathways such as MHC-II, APP, IL16, and CD86 were markedly suppressed." (PMID 41346577, 2025). "Although there is some evidence suggesting a potential link between APP and inflammation, particularly in neuroinflammatory processes, its role in systemic inflammation and sepsis is not well-established." (PMID 38167131, 2024). "Afterwards, fetuin-A levels started to increase, returning towards basal levels approximately 72 h post endotoxemia or sepsis, supporting the notion that fetuin-A functions as a negative APP in murine models of LSI." (PMID 21347455, 2011). "Additionally, the APP → CD74 signaling axis and the RPA1-centered regulatory network warrant in-depth experimental exploration to evaluate their potential as targets for therapeutic intervention in sepsis." (PMID 40625751, 2025). "When testing the impact that sepsis has on the memory of APP mice, we observed that all animals performed similarly in the NOR test before and after the acute sepsis event, regardless of their status, p > 0.05." (PMID 36135174, 2022).
Atrophy (10 papers, 2015 to 2026). Any weakening or degeneration, especially through lack of use. "This produced apoptotic cell death, hippocampal atrophy and memory impairments which were associated with APP recruitment to lipid rafts which increased Abeta and Tau." (PMID 36845656, 2023). "Research has indicated that hippocampal atrophy occurs early in AD, a finding consistent with the observed reduction in hippocampal volume in the APP/PS1 transgenic AD model mice of this study." (PMID 38419647, 2024). "In contrast, paroxetine significantly exacerbated the gliosis (p = 0.020) and also led to hippocampal atrophy (p = 0.010) in the APP/PSEN1 mice." (PMID 38259283, 2023). "Therefore, both SI induced Aβ-associated damage and SI itself are involved in the process of hippocampal atrophy in aged APP/PS1 mice." (PMID 25568286, 2015). "Previous findings indicate that both AD patients and APP/PS1 mice exhibit cortical and hippocampal atrophy." (PMID 40141679, 2025).
intracerebral hemorrhage (10 papers, 2011 to 2023). A cerebrovascular disorder characterized by bleeding into one or both cerebral hemispheres including the basal ganglia and the cerebral cortex. "The aggregation and cerebrovascular deposition of amyloid-β (Aβ) peptides, the products of sequential processing of the amyloid precursor protein (APP), in the walls of medium-sized and small brain vessels is the defining feature of CAA, a major cause of intracerebral hemorrhage." (PMID 39081996, 2023). "Summary of intracerebral haemorrhage and dup-APP status in the known kindreds." (PMID 27239286, 2016). "Therefore, it is not surprising that disruption of deposited Aβ from the vasculature by anti-Aβ antibodies significantly increased the frequency of intracerebral hemorrhage in APP tg mice." (PMID 22412990, 2012). "APP/London (APP/Ld) mice develop CAA at an earlier age in comparison with APPDutch mice, although the absence of the typical CAA-associated intracerebral haemorrhages limits the usefulness of such a model." (PMID 32414028, 2020).
lung carcinoma (10 papers, 2016 to 2025). "The hub genes CAT (HR = 0.6, P-value = 2.6e − 15, log2FC = − 1.3802) and APP (HR = 0.81, P-value = 0.0012, log2FC = − 1.1716) were significantly associated with an unfavorable overall survival in lung cancer patients." (PMID 36302939, 2022). "Despite a higher positive correlation (Pearson correlation coefficient R ≈ 0.84), we determined several known lung cancer-associated genes with high RS and low |log2FC|, such as TRIM28, APP, ESR1, MYC, and EGFR." (PMID 36229842, 2022). "In summary, we suggested for the first time that EIF3C is upregulated in lung cancer tissues and may enhance the proliferation and suppress the apoptosis of lung cancer cells by regulating the APP/HSPA1A/LMNB1 axis." (PMID 36157221, 2022). "EIF3C overexpression may facilitate the proliferation and hamper the apoptosis of lung cancer cells by regulating the APP/HSPA1A/LMNB1 axis." (PMID 36157221, 2022). "The orthologues were related to DHDH, ATP8B3, and P2RY1 genes, expressed in the lipid membrane, and directly related to skin and lung cancer genes (APP and APPBP2), suggesting that they may share mechanisms among these diseases." (PMID 36542226, 2022). "APP, especially the secreted form of APP, is upregulated in lung cancers." (PMID 26840089, 2016). "More work remains to be done, not only to examine the role of APP in lung cancer, but also to investigate the role that APLP1 and APLP2 might play in this particular type of cancer." (PMID 26840089, 2016). "Thus, we speculated that EIF3C may promote lung cancer tumorigenesis by regulating APP." (PMID 36157221, 2022). "Similarly, changes in AS events in lung cancer will also affect the transcripts of VEGFA, MACF1, APP, and NUMB genes, thereby promoting the process of tumorigenesis." (PMID 36466711, 2022). "Additionally, APP interacted with Amyloid-Beta Precursor Protein Binding Protein 2 (APPBP2), which is involved in non-small cell lung cancer (NSCLC), a type of cancer accountable for ~ 80% of all lung carcinoma patients." (PMID 36542226, 2022).
mental disorder (10 papers, 2013 to 2025). A disease that has its basis in the disruption of mental process. "If we want to assume a role of APP in the pathogenesis of mental illness, longitudinal studies are necessary to investigate psychiatric samples from youth to old age." (PMID 34679416, 2021). "One of the limits of the analysed studies is that the elderly population was examined, suggesting that further longitudinal studies are probably necessary to investigate APP metabolism in mental illness—from youth to old age." (PMID 34679416, 2021). "Our results suggest that CSF APP, GDNF, and NCAM-1 levels are associated with psychiatric disorders, and that CSF HGF, S100B, and VEGF receptor 2 levels are related to psychiatric symptoms." (PMID 32439851, 2020). "In conclusion, our data suggest the involvement of state- (i.e., HGF, S100B, and VEGF receptor 2) and trait (i.e., APP, GDNF, and NCAM-1) markers associated with neuroplasticity in the pathology of psychiatric disorders." (PMID 32439851, 2020). "Finally, it cannot be determined whether the alteration of expression, processing or clearance of significant proteins (i.e., APP, GDNF, HGF, NCAM-1, S100B, and VEGF receptor 2) results in the association with psychiatric disorders." (PMID 32439851, 2020). "APP is another protein that binds to TTR and its role in mental disorders is reported." (PMID 30034649, 2018). "Moreover, altered phospholipid metabolism has been well documented in several neurological and psychiatric diseases, including AD, in which PKC signaling is critical for the non-toxic degradation of the amyloid precursor protein (APP) and the inhibition of GSK3β, which controls tau phosphorylation." (PMID 32230887, 2020).